BDNF (brain derived neurotrophic factor)
Diseases named in the same sentence as BDNF in open-access papers (continued):
Sharing a sentence is not in itself a finding about the gene and the disease.
mood disorder (continued). "Physical activity has been reported to alter the progression of mood disorder neuropathology by optimizing neurotransmission function, brain-derived neurotrophic factor, endorphins, and cortisol." (PMID 34645802, 2021). "GSK-3b and phosphoinositide signaling pathways regulate BDNF, which has a complex role in mood disorders." (PMID 34295268, 2021). "Recently, BDNF was suggested to have a significance as predictive biomarker for the treatment of mood disorders." (PMID 32849818, 2020). "It postulates that mood disorders are related to decreased synthesis of brain-derived neurotrophic factor (BDNF) in the brain resulting in impaired synaptogenesis and neuronal activity." (PMID 32883977, 2020). "Hashimoto K, Shimizu E, Iyo M. Critical role of brain-derived neurotrophic factor in mood disorders." (PMID 32876194, 2020). "The neurotrophins most involved in mood disorder pathophysiology are the Brain-Derived Neurotrophic Factor (BDNF) and, to a lesser extent, the Glial-Derived Neurotrophic Factor (GNDF)." (PMID 32517269, 2020). "The changes in BDNF levels in blood or serum are more likely to reflect platelet activation and degranulation rather the neuronal damage in conditions such as MS, mood disorders, or neurodegeneration." (PMID 33031634, 2020). "Unfortunately, the specific mechanism of how BDNF participates in the regulation of the neuroimmune axis in mood disorders is still unclear and it is therefore necessary to conduct more in-depth research." (PMID 31231295, 2019). "BDNF/TrkB is a crucial synaptic regulator, which not only correlates with memory but also with mood disorders." (PMID 31338119, 2019). "Hippocampal neurogenesis and plasticity are thought to be involved in mental and mood disorders, and the BDNF is a key regulator of the formation and plasticity of neurons in brain circuits." (PMID 32082167, 2019). "The study on peripheral BDNF was originally driven by determining the pathophysiology of mood disorders, but BDNF has recently been applied to serve as a potential biomarker for promoting individualized medicine in psychiatry." (PMID 30794585, 2019). "Decreased plasma BDNF (pBDNF) levels have been proposed as a biomarker in illness phases of mood disorders." (PMID 31197968, 2019). "In this review, we summarize the latest progress in the role of BDNF in the neuroimmune axis regulation of mood disorders." (PMID 31231295, 2019). "Apart of the secretion of the pro-inflammatory cytokines, SD affects production of brain-derived neurotrophic factor (BDNF) while release of BDNF from astrocytes appears a key contributor to mood disorders." (PMID 30666218, 2018). "It is therefore possible that an interaction of BDNF, CREB1, GNAS, and POMC genes with exposure to chronic stress or traumatic life events increase the risk of cardiometabolic and mood disorders either simultaneously, or through mediating factors." (PMID 28117839, 2017). "Recently, our group reported the alteration of the irisin/BDNF axis in mood disorders accompanying chronic obstructive pulmonary disease (COPD)." (PMID 29217995, 2017). "Many studies investigated the serum or plasma level of single protein like BDNF in SZ or mood disorders, and suggested a potential role of BDNF as a biomarker of disease activity and treatment response." (PMID 28761093, 2017). "Our finding that changes in serum BDNF levels from baseline to follow-up differed among the four groups is suggestive of the pathophysiologic relationships of various subcategories of mood disorders and of their classification." (PMID 27070410, 2016). "Mean BDNF levels for the largest psychiatric disorder categories (mood disorders and anxiety disorders) were compared using ANOVA." (PMID 27121496, 2016). "Due to the opposite biological functions of pro-BDNF and m-BDNF in the neuronal system, it is important to discuss the roles of these two proteins in relation to mood disorders." (PMID 26091093, 2015).
mood disorder (continued). "The MAPK pathway is activated by BDNF through binding to the TrkB receptor, which further emphasizes the involvement of BDNF in mood disorders." (PMID 26091093, 2015). "Many previous studies examined the relationship between BDNF and mood disorders using a variety of study designs and analytical methods." (PMID 26091093, 2015). "The BDNF-pw results suggest a research avenue to study the link between mood disorders and cancers and to explore the common roles of BDNF in the two disease categories." (PMID 26091093, 2015). "We identified proteins that interact with BDNF and performed pathway-based analysis using large genome-wide association (GWA) datasets obtained for mood disorders." (PMID 26091093, 2015). "In this study, we adopted the systems biology perspective and applied several approaches to explore the features of BDNF in relation to mood disorders." (PMID 26091093, 2015). "In support of this, abstinent cocaine users diagnosed with both primary and cocaine-induced anxiety disorders exhibited a significant decrease in plasma BDNF with mood disorders." (PMID 25734326, 2015). "Based on reviewing the evidence in the literature, we considered that the more consistent findings for the involvement of BDNF in mood disorders come from protein level studies, which suggest roles for BDNF in the mechanisms of mood disorders." (PMID 26091093, 2015). "To summarize, we identified a few significant biological pathways for mood disorders that involve BDNF and BDNF-interacting molecules." (PMID 26091093, 2015). "Pro-BDNF is important in the response to stress; the literature review suggests the necessity of studying both pro- and m-BDNF with regard to mood disorders." (PMID 26091093, 2015). "For example, it has been postulated that BDNF affects mood disorders through protein p11 by activating tissue plasminogen activator (tPA)/plasminogen activity, cutting pro-BDNF to increase the production of m-BDNF and leading to an antidepressant effect." (PMID 26091093, 2015). "The effect of the BDNF gene on mood disorder is too weak to be detected by family-based linkage study design." (PMID 26091093, 2015). "A variety of studies have been conducted to investigate the relationships between BDNF and mood disorders." (PMID 26091093, 2015). "Because of their importance in maintaining the growth, survival, and function of neurons, exploring the potential roles of BDNF in brain disorders has been a long-standing focus, especially for mood disorders." (PMID 26091093, 2015). "Our findings are consistent with the literature because BDNF concentrations in cocaine users diagnosed with mood disorders, both primary and cocaine-induced, were found to be decreased." (PMID 25734326, 2015). "Accumulating evidence suggests the neurotrophin Brain Derived Neurotrophic Factor (BDNF) is reduced in mood disorders." (PMID 26539329, 2015). "Studies have demonstrated a reciprocal relationship between mood disorders and BDNF levels, both in circulation as well as in the brain." (PMID 26501066, 2014). "This species difference has greatly hampered mechanistic studies into this interesting and consistent finding of the relationship between mood disorders and serum BDNF levels." (PMID 24817844, 2014). "A comprehensive review of the role of BDNF in mood disorders is beyond the scope of this review, but some remarks are useful to provide a perspective for the rodent data reviewed below." (PMID 24817844, 2014). "Dysfunctional HTT affects cellular pathways that are involved in mood disorders or in the response to antidepressants, including BDNF/TrkB and serotonergic signaling." (PMID 24795586, 2014). "This review will summarize the results from these BDNF and TrkB genetic models that are related to mood disorders." (PMID 24817844, 2014).
mood disorder (continued). "Four of the most consistently replicated variants associated with mood disorder occur in genes important for synaptic function: ANK3 (rs10994336), BDNF (rs6265), CACNA1C (rs1006737), and DGKH (rs1170191)." (PMID 24944871, 2014). "More studies are needed to elucidate the possible mechanisms by which n-3 PUFAs consumption affects BDNF levels and influences the vulnerability to psychiatric and mood disorders, especially during certain life stages such as adolescence." (PMID 24593295, 2014). "BDNF has been implicated in the physiopathology of mood disorders, and is thus the most obvious candidate linking HTT to mood disorders." (PMID 24795586, 2014). "Interactions between brain-derived neurotrophic factor (BDNF) and mood disorders have also been suggested." (PMID 24971450, 2014). "Findings suggest that BDNF and social support seems to be a logical target as it seems to be the bridge linking mood disorders and alcohol consumption." (PMID 26501066, 2014). "The role of BDNF in mood disorders has received more attention than other members of the neurotrophin family." (PMID 25202283, 2014). "Recently it has been proved that BDNF is involved in not only stress-related mood disorder, but also some human reproductive diseases, such as polycystic ovary syndrome and infertility." (PMID 23284991, 2012). "Although it is generally accepted that chronic stress impairs female reproduction and decreases the expression of BDNF in limbic structures of central nervous system, which contributes to mood disorder." (PMID 23284991, 2012). "Increased BDNF expression inhibits oxidative stress and protects against neuronal death, playing vital roles in regulating learning and memory, cognitive function, and mood disorders." (PMID 41517237, 2026). "Stress and mood disorders are also known to decrease BDNF secretion." (PMID 41311851, 2025). "However, recent systematic reviews and meta-analyses in mood disorders and neurodegenerative diseases emphasise both the variability and methodological challenges of using peripheral BDNF and CRP for biomarker-informed stratification." (PMID 41367212, 2025). "This hormonal dysregulation also affects the central nervous system (CNS), particularly influencing the synthesis of brain-derived neurotrophic factor (BDNF), as well as other neurotransmitters such as serotonin, increasing the vulnerability to mood disorders in women with endometriosis." (PMID 40075795, 2025). "Therefore, higher levels of BDNF are also unfavorable: changes in the individual BDNF expression may be a helpful diagnostic tool for assessing the impairment of the cognitive functions and mood disorders as well as a marker of the effectiveness of pharmacological treatments." (PMID 41562905, 2025). "The BDNF system is important for the pathogenesis and treatment of mood disorders." (PMID 40283904, 2025). "Studies have shown that sleep disorders may alter the levels of brain-derived neurotrophic factor, which plays a key role in the pathophysiology of stress-related mood disorders." (PMID 41210125, 2025). "BDNF is a critical growth factor involved in neural development, regeneration, synaptic plasticity, and neurogenesis, particularly in brain regions like the HIPP, which are linked to mood disorders." (PMID 40108902, 2025). "Given this background, the aim of this study is to evaluate the effects of green tea and its bioactive compounds—specifically L-theanine and epigallocatechin gallate (EGCG)—on mood disorder symptomology and BDNF levels using evidence from published randomized controlled trials." (PMID 40722728, 2025). "Restoring intestinalbarrier integrity and addressing gut inflammation could potentially help tomodulate BDNF levels and dopamine function, offering novel therapeutic avenuesfor managing mood disorders and other neuropsychiatric conditions." (PMID 41523964, 2025).
mood disorder (continued). "Although the role of BDNF in the manifestation of mood disorders such as anxiety has been well known for some time, determining whether BDNF acts as an anxiolyic or anxiogenic regulator is far from resolved." (PMID 38228888, 2024). "The lower BDNF levels observed in mood disorder groups could be attributed to BDNF's role in neuronal plasticity and survival." (PMID 39493096, 2024). "Furthermore, irisin’s activation of BDNF signaling is crucial for modulating dopamine release, and its antidepressant effects are important not only for mood disorders but also for managing neuropsychiatric symptoms in AD patients." (PMID 39769243, 2024). "Also, preliminary evidence indicates that uPA modulates BDNF activity that is known to be involved in the pathogenesis of mood disorders." (PMID 39766310, 2024). "This pattern suggests that BDNF may be a more robust biomarker for mood disorder severity, particularly in depressive and manic episodes." (PMID 39493096, 2024). "Numerous studies have shown that the peripheral (serum and/or plasma) BDNF levels are lower in patients with mood disorders during manic/mixed and depressive episodes compared to matched healthy controls, and that effective treatments can normalize these levels." (PMID 39595869, 2024). "Although more research is needed to understand mechanistic links between uPA activation, BDNF maturation, and emotion diseases, our study may open new therapeutic avenues focused on tackling stress-induced mood disorders." (PMID 39766310, 2024). "Several recent studies have shown that peripheral (serum and/or plasma) levels of BDNF are lower in patients suffering from mood disorders during manic/mixed and depressive episodes than in matched healthy controls and that effective treatments are capable of normalizing them." (PMID 38396487, 2024). "Despite substantial evidence supporting the role of BDNF in mood disorders, there remain unresolved questions regarding the relationship between BDNF levels, its gene regulation (specifically through methylation) and psychiatric outcomes in the context of work-related stress." (PMID 39595869, 2024). "BDNF reduction may impair neuroplasticity, contributing to the development and maintenance of mood disorders." (PMID 39493096, 2024). "Moreover the level of BDNF with SLC64 is utilized as a biomarker to diagnose mood disorders in diseased/healthy subjects, and there are many other genes (NR3C1 and FKBP5) that have also been linked to the early diagnosis of mood disorders." (PMID 36766442, 2023). "Nutraceuticals affect factors that could potentially impact the onset of mood disorders: monoamines and brain-derived neurotrophic factor (BDNF) concentrations, neuroinflammation, oxidative stress, and sleep quality." (PMID 37759862, 2023). "Thus, BDNF has been studied with great interest regarding mood disorders, and some antidepressants act upon BDNF-TrkB." (PMID 35887370, 2022). "BDNF genotype and expression may affect the levels of the BDNF protein and/or its neuroplasticity, thus influencing the development of mood disorders." (PMID 35205345, 2022). "BDNF (brain-derived neurotrophic factor) is a growth factor involved in various mood disorders." (PMID 35765004, 2022). "Elevated BDNF levels may act as a possible protective or compensatory mechanism in individuals whose first-degree relatives are diagnosed with mood disorders." (PMID 34575175, 2021). "Both lipid metabolism and BDNF play a role in mood disorders." (PMID 34093436, 2021). "Moreover, from a molecular point, yoga promotes brain health by increasing brain-derived neurotrophic factor (BDNF)) which is a crucial neurotrophin in the management of mood disorders." (PMID 34454533, 2021). "However, the finding of increased GDNF in mood disorders and increased BDNF with antidepressant treatment supports a role of growth factors in mood disorder or its medication treatment." (PMID 34078872, 2021).
mood disorder (continued). "The relationship between mood disorder and serum BDNF levels is complex in patients with RA." (PMID 33673283, 2021). "In general, BDNF plays a role in the pathophysiology of schizophrenia and mood disorders." (PMID 33850645, 2021). "Serum brain-derived neurotrophic factor (BDNF) reflects state changes in mood disorders." (PMID 32883977, 2020). "There are several pieces of evidence about the role of BDNF in brain function and mood disorders." (PMID 32942585, 2020). "Conversely, BDNF can promote glia growth and proliferation and contribute to the chronic inflammatory state of the brain and neurotoxicity observed in several mood disorders." (PMID 32517269, 2020). "In addition, many factors contributed to limiting peripheral BDNF as a reliable biomarker for mood disorders." (PMID 32517269, 2020). "However, the potential mechanism for BDNF to affect mood disorders, by participating in changes in the neural-immune axis, has not been elucidated." (PMID 31231295, 2019). "Several studies have shown that BDNF may be indispensable to the neuroimmune regulation of mood disorders." (PMID 31231295, 2019). "Therefore, in this review, we focus on the recent progress of BDNF in influencing mood disorders, by participating in alterations of the neuroimmune axis." (PMID 31231295, 2019). "However, BDNF has been linked to a variety of other psychiatric disorders, especially mood disorders, and hence it is yet unclear how specific the BDNF effects are in relation to PTSD symptomatology." (PMID 30816289, 2019). "Also, further investigations have to be achieved regarding the role of the BDNF/TrkB complex in mood disorders, in order to have a better knowledge of how to correct the dysregulation of this system in mental illness." (PMID 29961124, 2018). "Previous studies found a gender-specific influence of BDNF on mood disorders." (PMID 29357818, 2018). "Accumulating evidence indicates the involvement of BDNF in the pathophysiology of mood disorders." (PMID 29357818, 2018). "However, other preclinical studies showed an association between low levels of BDNF in VTA with anhedonia, while patients with mood disorders were characterized by low TrkB expression in postmortem striatum and low circulating levels of BDNF." (PMID 29531524, 2018). "In addition, SD increases serum levels of brain-derived neurotrophic factor (BDNF), which is related to sleep, cognition and learning, The BDNF released from astrocytes is also known to be associated with mood disorders." (PMID 30666218, 2018). "However, the significant variation between available assays prevents the use of serum BDNF (and other neurotrophins) levels as a reliable biomarker for mood disorders." (PMID 29961124, 2018). "BDNF level may be a biomarker of mood disorders and may be a central factor in the network of multimorbidity in old populations." (PMID 29312105, 2017). "Clinical and animal studies have reported decreased BDNF levels in human patients or depressive animals and the normalization of its levels by antidepressant treatment, making BDNF a potential biomarker for mood disorders." (PMID 28210212, 2017). "When this analysis was repeated with the inclusion of mood disorders and anxiety disorders as covariates, neither was significantly associated with BDNF level β = −0.79, P = 0.54 for mood disorder; β = 2.20, P = 0.07 for anxiety disorder)." (PMID 27121496, 2016). "The link between low levels of hippocampal BDNF and mood disorders has been dubbed the neurotrophin hypothesis, whereby enhancement in BDNF signaling is observed in the hippocampus after administration of antidepressants." (PMID 26257661, 2015). "Dysfunction of the BDNF-related pathways might be one of the key points leading to mood disorders in response to environmental stimuli." (PMID 26091093, 2015).